CD79B (CD79b molecule)
Diseases named in the same sentence as CD79B in open-access papers (continued):
Sharing a sentence is not in itself a finding about the gene and the disease.
follicular lymphoma (5 papers, 2013 to 2025). Follicular lymphoma is a form of non-Hodgkin lymphoma characterized by a proliferation of B cells whose nodular structure of follicular architecture is preserved. "The CD79b-directed antibody drug conjugate (ADC) polatuzumab vedotin targets macrophages in follicular lymphoma." (PMID 39963673, 2025). "A single case of follicular lymphoma (n = 1) showed a bright expression of CD79b." (PMID 36483322, 2022). "Recurrent mutations of genes involved in epigenetic regulation (e.g. KMT2D, CREBBP, and EZH2), JAK-STAT pathway (e.g. SOCS1, STAT6), immune signaling (i.e. TNFRSF14), and BCR/NFKB signaling (e.g. CARD11, CD79B) were previously reported in follicular lymphoma cases." (PMID 35795062, 2022).
agammaglobulinemia (4 papers, 2018 to 2024). A decreased level of serum immunoglobulins. "Agammaglobulinemia with other inherited pattern were also concluded: AR agammaglobulinemia was associated with mutations in several other genes such as IGHM, IGLL1, CD79A, CD79B, BLNK, PIK3R1, and TCF3 genes; AD-related agammaglobulinemia was also found with LRRC8A and TCF3 gene mutations." (PMID 36140582, 2022).
melanoma (4 papers, 2021 to 2024). A malignant, usually aggressive tumor composed of atypical, neoplastic melanocytes. "Our work suggests that CD79b+ neutrophils are associated with early-stage melanoma." (PMID 38022639, 2023). "Using machine learning, we found that CD79b expression among neutrophils in the blood ranks highly in importance for distinguishing healthy from melanoma blood." (PMID 38022639, 2023). "CD79b+ neutrophils were elevated in melanoma subjects not only as a percentage of total blood cells but also as a percentage of total neutrophils, suggesting that peripheral neutrophil heterogeneity has changed in cancer." (PMID 38022639, 2023). "CD79b+ neutrophils were quantified in blood from 41 human melanoma subjects and in the bone marrow of 5, and in the blood of 12 healthy human donors, using flow cytometry." (PMID 38022639, 2023). "In summary, our study defines CD79b expression among neutrophils as correlative with early-stage melanoma incidence." (PMID 38022639, 2023). "AI-mediated machine learning analysis of neutrophils from subjects with melanoma confirmed that CD79b expression among peripheral blood neutrophils is highly important in identifying melanoma incidence." (PMID 38022639, 2023). "We show that CD79b+ neutrophils are specifically elevated in the blood of subjects with early-stage melanoma." (PMID 38022639, 2023). "To more thoroughly define the relationship between CD79b+ neutrophils, CD79b- neutrophils, and B cells in healthy human bone marrow and melanoma patient blood, we sorted and profiled these populations by bulk RNA-sequencing." (PMID 38022639, 2023). "As the healthy controls in this cohort possessed a lower mean age than the melanoma subjects, we asked if the presence of peripheral CD79b+ neutrophils correlated with age." (PMID 38022639, 2023). "The CD79b+ neutrophil phenotype aligns with these antigen-presenting neutrophils, as CD79b+ neutrophils are also present in the blood of melanoma patients at the early stages of disease." (PMID 38022639, 2023). "Because CD79b+ neutrophils are elevated in the blood of melanoma patients compared to healthy individuals, we tested their predictive importance using random forest-based machine learning with ten-fold cross-validation." (PMID 38022639, 2023). "The current work, however, does yet fully define the function or elucidate the pro- versus anti-tumor properties of CD79b+ neutrophils in melanoma." (PMID 38022639, 2023). "Regardless of results related to function, the current data suggest CD79b+ neutrophils enrichment in early-stage melanoma patients makes them poised to be developed further as a biomarker of disease." (PMID 38022639, 2023). "We next measured several neutrophil-specific functions in CD79b+ neutrophils compared to other blood neutrophils in subjects with melanoma." (PMID 38022639, 2023). "Further work in mouse models and exploration in larger datasets with relevant outcome data is needed to define CD79b+ neutrophils as a functional subset in melanoma fully." (PMID 38022639, 2023). "As CD79b was previously unexplored in neutrophils, we evaluated CD79b expression in neutrophils from independent cohorts of melanoma subjects using flow cytometry." (PMID 38022639, 2023). "CD79b+ neutrophils took up a greater level of Zymosan and ZsGreen+ tumor cells than CD79b- neutrophils obtained from the same melanoma subject blood sample." (PMID 38022639, 2023). "As CD79b+ neutrophils were still rare among blood cells from melanoma patients, sourcing samples from a cooperative biobank was critical to obtain the number of samples and cells needed for this study." (PMID 38022639, 2023). "We again found that CD79b+ neutrophils were elevated in the peripheral blood of melanoma subjects." (PMID 38022639, 2023). "Next, we asked whether CD79b+ neutrophils can be generated by co-culturing B cells and neutrophils from melanoma patient blood." (PMID 38022639, 2023).
melanoma (continued). "Importantly, we found that CD79b+ neutrophils were enriched in the blood of melanoma subjects with stage I and II tumors but were diminished in subjects with stage III/IV tumors." (PMID 38022639, 2023). "On average, 60% of CD79b+ neutrophils expressed CD197 in melanoma patient blood." (PMID 38022639, 2023). "We hypothesize that CD79b expression among neutrophils could be an early biomarker of melanoma incidence." (PMID 38022639, 2023). "We identified CD79b+ neutrophils (CD3-CD56-CD19-Siglec8-CD203c-CD86LoCD66b+CD79b+) that are normally restricted to the bone marrow in healthy humans but appear in the blood of subjects with early-stage melanoma." (PMID 38022639, 2023). "Additionally, the major finding, the presence of CD79b+ neutrophils in melanoma patient blood, was repeated in the cohort age-match cohort sourced from the University of Southampton, where healthy donor and matched melanoma patient samples were processed within hours of the blood draw." (PMID 38022639, 2023). "Using flow cytometry, we found that CD79b+ neutrophils expressed higher levels of the antigen presentation-related proteins, namely CD40, CD80, and HLA-DR, compared to other neutrophils in melanoma subjects." (PMID 38022639, 2023). "We found that CD79b+ neutrophils were elevated in the blood of melanoma patients with early-stage disease rather than late-stage disease." (PMID 38022639, 2023). "CD79b+ neutrophils were present in the bone marrow but absent from the blood of healthy human donors but were elevated in the blood of melanoma subjects." (PMID 38022639, 2023). "Interestingly, CD79b expression in blood neutrophils showed a high level of importance rank, and a similarly high level of importance rank compared to CD117, in distinguishing melanoma from healthy subjects." (PMID 38022639, 2023).
non-Hodgkin lymphoma (4 papers, 2017 to 2025). Distinct from Hodgkin lymphoma both morphologically and biologically, non-Hodgkin lymphoma (NHL) is characterized by the absence of Reed-Sternberg cells, can occur at any age, and usually presents as a localized or generalized lymphadenopathy associated with fever and weight loss. "Our study analyzed 13 studies (Phase I–III) and 1533 Non-Hodgkin Lymphoma (NHL) patients to evaluate the effectiveness of polatuzumab vedotin as a CD79B gene-targeting drug using a meta-analysis approach." (PMID 40725080, 2025). "Thus, this study aimed to evaluate the efficacy of polatuzumab vedotin as a CD79B gene-targeting drug across different subgroups of Non-Hodgkin Lymphoma patients by adopting a systematic review and meta-analysis research approach." (PMID 40725080, 2025). "The selection and screening of research articles related to the study aim “Efficacy of polatuzumab vedotin as CD79B gene targeting drug for treatment of Non-Hodgkin Lymphoma patients” was performed according to the PRISMA guidelines in this systematic review and meta-analysis." (PMID 40725080, 2025). "This study aimed to evaluate the effectiveness of polatuzumab vedotin as a CD79B gene-targeting drug for the treatment of Non-Hodgkin Lymphoma (NHL) by adopting a systematic review and meta-analysis research approach." (PMID 40725080, 2025). "Polatuzumab vedotin (PoV) is a novel antibody-drug conjugate that targets CD79B for the treatment of Non-Hodgkin Lymphoma (NHL)." (PMID 40725080, 2025).
systemic lupus erythematosus (4 papers, 2021 to 2025). An autoimmune multi-organ disease typically associated with vasculopathy and autoantibody production. "CD79b-targeted ADCs, initially designed for B-cell malignancies, have shown efficacy in preclinical models of systemic lupus erythematosus (SLE) by depleting autoreactive B cells while sparing protective immunity." (PMID 41012501, 2025). "This is illustrated by the overexpression of CD79a and CD79b, molecules involved in the transduction of BCR signal, and of CD81 whose co-expression with BAFFR and CD38 in transitional B-cells is associated with active systemic lupus erythematosus." (PMID 39185406, 2024).
acute lymphoblastic leukemia (3 papers, 2021 to 2024). Leukemia with an acute onset, characterized by the presence of lymphoblasts in the bone marrow and the peripheral blood. "Unlike the prevalent expression of CD79a, CD79b is typically absent in pre-B-acute lymphoblastic leukemia (ALL), plasma cell tumors, and chronic lymphocytic leukemia (CLL) cases." (PMID 39682155, 2024).
breast DLBCL (3 papers, 2020 to 2023). "Seven cases of breast DLBCL were included in our study, and MYD88L265P and CD79B mutations were found in four and three cases, respectively, consistent with the results of previous studies." (PMID 37706649, 2023). "In breast DLBCL, MYD88L265P (57.1%), CD79B mutation (42.9%), and CDKN2A/B loss (71.4%) were found at high frequencies, which were similar to the mutation patterns of DLBCL of immune‐privileged sites compared with DLBCL NOS." (PMID 37706649, 2023). "In primary breast DLBCL, MYD88 L265P and CD79B mutations were detected in 58.7% and 33.3% of cases, respectively." (PMID 33050534, 2020).
lung carcinoma (3 papers, 2020 to 2023). "A subset of the 11 gene signature has recently been reported in the context of lung cancer, either as an oncogenic driver (e.g. CD79B) or a prognostic marker (e.g. TRAF3IP3, SKAP2, and SS18L2)." (PMID 33287695, 2020). "Currently, there is no in-depth study of the biological mechanism of CD79B in lung cancer." (PMID 37622116, 2023).
MALT lymphoma (3 papers, 2013 to 2025). An indolent, extranodal type of non-Hodgkin lymphoma composed of small B-lymphocytes (centrocyte-like cells). "However, no CD79B mutations were detected in 16 gastric MALT lymphoma cases analyzed in the same study." (PMID 23378931, 2013).
mantle cell lymphoma (3 papers, 2022 to 2024). Mantle cell lymphoma is a rare form of malignant non-Hodgkin lymphoma affecting B lymphocytes in the lymph nodes in a region called the ``mantle zone''. "Similar anti-tumor efficacy of CD19 and CD79b (a pan B-cell marker) CAR T-cells in models of mantle cell lymphoma (MCL) was reported." (PMID 35199207, 2022). "Nongenetic mechanisms of resistance or adaptation to ibrutinib have been described in mantle cell lymphoma (MCL) and diffuse large B cell lymphoma (DLBCL) and involve CD79b overexpression or compensatory PI3K activation." (PMID 39436708, 2024).
B-cell neoplasm (2 papers, 2024). A group of heterogeneous lymphoid tumors generally expressing one or more B-cell antigens or representing malignant transformations of B-lymphocytes. "In contrast, CD79b finds widespread expression in mature B-cell neoplasms, encompassing 80–90% of cases." (PMID 39682155, 2024). "CD79b exhibits a nearly exclusive expression pattern on B cells and B-cell neoplasms." (PMID 39682155, 2024).
celiac disease (2 papers, 2019 to 2025). An autoimmune genetic disorder with an unknown pattern of inheritance that primarily affects the digestive tract. "NHL and celiac diseaseCD79B (NHL) and IL2 (Celiac Disease) the relationship between IL2’s function in T-cell activation in Celiac disease and CD79B’s role in B-cell receptor signaling in NHL suggests a possible link between lymphocyte dysregulation in both conditions." (PMID 40321894, 2025).
CNS DLBCL (2 papers, 2022). "In present study, we attempted to classify primary CNS DLBCLs into two biologically relevant subgroups based on the mutational status of CD79B and PIM1 by targeted exome sequencing covering 413 genes." (PMID 35223507, 2022). "Although we established such a molecular classification for CNS DLBCL in present study, the underlying mechanism by which CD79B and PIM1 mutational status impact the outcome of primary CNS DLBCL after HD-MTX-based polychemotherapy remains unknown." (PMID 35223507, 2022). "CNS DLBCLs frequently harbored MYD88, CD79B and/or PIM1 mutations." (PMID 35223507, 2022). "Therefore, in terms of application, our data suggest that a new molecular classification based on the mutational status of CD79B and PIM1 could be used to predict patient outcomes in CNS DLBCL." (PMID 35223507, 2022). "CNS DLBCL patients without PIM1 and CD79B mutations had inferior long-term survival after HD-MTX-based chemoimmunotherapy in the present study, even though they were younger and had a lower MCD subtype." (PMID 35223507, 2022).
COVID-19 (2 papers, 2021 to 2023). A disease caused by infection with severe acute respiratory syndrome coronavirus 2. "By searching for DTGs associated with IRGs shared between COVID-19 and IS, we identified eight DEGs interacting with two known databases of drug targets: JAK2, ORM1, RNASE2, TNFSF13B, CYBB, EIF2AK2, CD79B and CAMP." (PMID 36969251, 2023). "Specifically, in the COVID-19 patient’s B cells, we detected a substantial increase in the expression of CD52, CD74, CD22 and CD79B and a decrease in CXCR4, CD69, INFGR1, PTPRC and LAMP1 transcripts with respect to control-derived B cells." (PMID 34944610, 2021).
Hodgkins lymphoma (2 papers, 2013 to 2014). A heterogeneous group of malignant lymphoid neoplasms of B-cell origin characterized histologically by the presence of Hodgkin and Reed-Sternberg (HRS) cells in the vast majority of cases. "FISH and PCR analyses showed that these two Hodgkin lymphoma-derived hybrid tumors displayed both hamster and human DNA in the same nuclei by FISH, while also retaining the human genes, CD74, CXCR4, CD19, CD20, CD71, CD79b, and VIM." (PMID 25259521, 2014). "The prevalence of B-cell restricted genes (CD19, CD20, and CD79b) suggests that this uniform population may be the clonal initiating (malignant) cells of Hodgkin lymphoma, despite their not showing translation to their respective proteins by immunohistochemical analysis." (PMID 23405135, 2013).
lymphoid neoplasm (2 papers, 2013 to 2023). A neoplasm composed of a lymphocytic cell population which is usually malignant (clonal) by molecular genetic and/or immunophenotypic analysis. "We have reviewed the complex role of CD79a/CD79b in multiple aspects of normal B cell biology and how is the normal BCR signaling affected by lymphoid neoplasms associated CD79A/CD79B mutations." (PMID 38203179, 2023).
myeloid malignancies (2 papers, 2025 to 2026). "The findings generate hypotheses for future mechanistic studies and evaluation of CD79B as a potential biomarker in myeloid malignancies." (PMID 41625736, 2026).
non-small cell lung carcinoma (2 papers, 2023). A group of at least three distinct histological types of lung cancer, including non-small cell squamous cell carcinoma, adenocarcinoma, and large cell carcinoma. "In gastric and non-small cell lung cancer, a decreased CD79B expression was related to shorter survival as well as tumor malignancy." (PMID 37671167, 2023). "As a tumor suppressor gene, when the expression of CD79B decreases, the vitality, proliferation, migration, and invasion capabilities of non-small cell lung cancer cells increase, indicating that CD79B may have some biological significance in tumor treatment and is worth studying further." (PMID 37622116, 2023). "Thus, CD79B is a protective factor in gastric and non-small cell lung cancers, which corroborated the finding that TNBC patients exhibiting elevated levels of CD79B expression demonstrated a more favorable prognosis." (PMID 37671167, 2023).
Autoimmunity (1 paper, 2023). The occurrence of an immune reaction against the organism's own cells or tissues. "Notably, Ian R Hardy and colleagues have proposed the use of monoclonal antibodies targeting CD79B as a means to collectively suppress B cells and prevent autoimmunity, with the added benefit of facilitating rapid immune recovery, unlike other approaches that induce B cell death." (PMID 37849750, 2023).
bone lymphomas (1 paper, 2022). "Targetable alterations are scarce in bone lymphoma; however, in contrast to previous publications, we identified one case with a MYD88 and one case with a CD79B mutation." (PMID 36051079, 2022).
brain tumors (1 paper, 2023). "Rapid genotyping of MYD88 L265P and CD79B Y196 mutations is quite effective for intraoperative molecular diagnosis of PCNSL because it is sometimes difficult to distinguish PCNSL from inflammatory changes or other brain tumors." (PMID 36478416, 2023).
cervical cancer (1 paper, 2022). A primary or metastatic malignant neoplasm involving the cervix. "Relationship between CD79B expression in cervical cancer and clinicopathological factors." (PMID 36406115, 2022).
chronic leukemia (1 paper, 2025). A slowly progressing leukemia characterized by a clonal (malignant) proliferation of maturing and mature myeloid cells or mature lymphocytes. "Flow cytometry (chronic leukemia immunophenotyping) revealed CD5 positivity, CD23 positivity, Sm Ig weak positivity, CD22 or CD79b weak, CD10 negativity, and FMC7 negativity." (PMID 40815495, 2025).
Chronic Myelogenous Leukemia (1 paper, 2021). "PAX5, CD19 and CD79b are all absent in K562 (a non-B Chronic Myelogenous Leukemia cell line)." (PMID 33452395, 2021).
colitis (1 paper, 2008). Inflammation of the colon. "Thus, TNBS colitis was characterized by an absence of significant changes in markers of T cells (Thy1, Tcrb, Tcrg, Zap70, Lck), B cells (Ptprc -B220-, Ms4a1 -Cd20-, Cd22, Cd79b) and NK cells (Baat, Ncam1 -Cd56-, B3gat1 -Cd57-)." (PMID 18928539, 2008).
head and neck cancer (1 paper, 2023). A primary or metastatic malignant neoplasm affecting the head and neck. "Further, we found CD79b+ neutrophils present in tumors of subjects with head and neck cancer." (PMID 38022639, 2023).
lung adenocarcinoma (1 paper, 2023). A carcinoma that arises from the lung and is characterized by the presence of malignant glandular epithelial cells. "The results of immunohistochemicals show that the expression of CD79B and PTK2B in lung adenocarcinoma is higher than tissue next to cancer." (PMID 37622116, 2023).
lymphopenia (1 paper, 2018). Reduction in the number of lymphocytes. "In contrast, DEGs found exclusively during EBOV infection were mostly involved with dysregulation of blood circulation and vasculature development as well as lymphopenia as evidenced by a decrease in CD79B, CD3, CD8, NFATC3, and PRF1." (PMID 30723475, 2018).
metastatic melanoma (1 paper, 2014). A melanoma that has spread from its primary site to another anatomic site. "Patients with shorter OS showed enhanced levels of CD79b, part of the B-cell receptor complex (BCR), implicating an elevation of B-lymphocytes in LNs resected from stage III metastatic melanoma patients with poor survival outcomes." (PMID 24435119, 2014). "Here, an accumulation of B-lymphocytes, indicated by elevated CD79b, may be related to lymphangiogenesis, increased lymph flow and subsequent tumor dissemination in stage III metastatic melanoma patients with reduced OS." (PMID 24435119, 2014).